HDAC6 (histone deacetylase 6)
Diseases named in the same sentence as HDAC6 in open-access papers (continued):
Sharing a sentence is not in itself a finding about the gene and the disease.
colon cancer (continued). "These clinical data indicate that TAK1 phosphorylation is positively correlated with HDAC6 expression and is related to the proportion of M2 macrophage infiltration in colon cancer specimens." (PMID 36270986, 2022). "In summary, these results show that the activation of TAK1 and downstream signal transduction play a critical role in the process, which HDAC6 promotes the release of sIL-6R and the polarization of M2 macrophages in colon cancer." (PMID 36270986, 2022). "Collectively, these results suggest MIIP-S303 phosphorylation maintains RelA Ac-K310 levels in colon cancer cells in vivo through its antagonistic effects on HDAC6, thus facilitates tumor metastasis." (PMID 29038521, 2017). "The positive correlation between K-ras mutants and high level of HDAC6 expression in colon cancer patients prompted us to test if K-ras mutants induce HDAC6 expression." (PMID 26848526, 2016). "Because HDAC6 is comparatively highly expressed in colon cancer cells, we propose that high HDAC6 expression in tumours gives rise to a lowly acetylated but highly secreted form of GRP78." (PMID 27460191, 2016). "In this study, we find that HDAC6 protein level is significant increased in 7 of 12 (59%) tumor tissues compared to controls in colon cancer patients." (PMID 26848526, 2016). "It has long been known that HDAC6 is overexpressed in colon cancers, therefore its inhibition may represent a targeted-based strategy." (PMID 41458974, 2025). "In Ewing sarcoma, HDAC6 modulates acetylation of SP1 and its binding to activating promoter regions, and a reduction in SP1 acetylation was shown to result in loss of promoter binding associated with cell cycle arrest in colon cancer." (PMID 39800760, 2025). "Furthermore, HDAC6 regulates apoptosis by the deacetylation of the antiapoptotic protein survivin, promoting its exit from the nucleus, which inhibits apoptosis of colon cancer cells." (PMID 38258065, 2023). "Thus, we investigated the protein levels of phosphorylated TAK1, TAK1, and HDAC6 in human colon cancer." (PMID 36270986, 2022). "In our study, we determined that HDAC6 could promote sIL-6R release by colon cancer cells to regulate macrophage polarization." (PMID 36270986, 2022). "Similarly, the knockdown of HDAC6 in colon cancer cells inhibited cocultured macrophage M2 polarization in vitro." (PMID 36270986, 2022). "Notably, the expression of phosphorylated TAK1 was positively correlated with HDAC6 expression and macrophage M2 polarization in human colon cancer tissues." (PMID 36270986, 2022). "To evaluate the correlation between HDAC6 expression and macrophage M2 polarization in the colon cancer immune microenvironment, we first collected tissue samples from 52 patients with stage II-IV colon cancer for multiplex immunohistochemistry (mIHC) analysis." (PMID 36270986, 2022). "Histone deacetylase 6 (HDAC6), a member of the HDAC family, has been identified as a potential therapeutic target for tumor therapy, but the function and underlying mechanisms of HDAC6 in colon cancer are incompletely characterized." (PMID 36270986, 2022). "Therefore, we confirmed that HDAC6 affects sIL-6R release in colon cancer cells by regulating the activity of ADAM17." (PMID 36270986, 2022). "HDAC6 holds promise as a tumor potential prognostic marker, especially in colon cancer." (PMID 34485153, 2021). "have shown that the HDAC6 selective inhibitor ACY1215 could play an effective role in inhibiting colon cancer cell growth, migration, invasion, and triggering apoptosis in colon cancer cells, and thereby elevating the efficacy of 5-FU." (PMID 33954114, 2021).
colon cancer (continued). "Additionally, SET7/9 has a tumor suppressor function which involves it interacting with HDAC6 and suppressing HDAC6-mediated activation of the ERK signaling pathway in colon cancer." (PMID 34201935, 2021). "Also, silencing of HDAC6 decreased cell migration, as has already been demonstrated in colon cancer after treatment with a HDAC6 inhibitor, A452." (PMID 34073238, 2021). "More importantly, increased cellular proliferation and migration in SPOP-depleted HCT116 colon cancer cells could be partly reversed by additional depletion of HDAC6, suggesting that HDAC6 is a key downstream effector for SPOP tumor suppressor function." (PMID 28599312, 2017). "Western blotting showed higher expression of HDAC6 protein in 7 (59%) tumor tissues compared to controls, suggesting that HDAC6 may be involved in human colon cancer development." (PMID 26848526, 2016). "Therefore, HDAC6 represents a promising therapeutic target related to the TME in colon cancer." (PMID 36270986, 2022). "Therefore, the phosphorylation of TAK1 and HDAC6 may be potential biomarkers for human colon cancers." (PMID 36270986, 2022). "Interestingly, we found that HDAC6 could promote the release of sIL-6R by colon cancer cells, thereby further affecting macrophage M2 polarization." (PMID 36270986, 2022). "However, it is unclear what causes HDAC6 up-regulation in other colon cancer patients without K-ras activating mutations." (PMID 26848526, 2016). "Interestingly, we demonstrate that HDAC6 is highly expressed in colon cancer cells." (PMID 27460191, 2016). "Specifically, HDAC6, a member of the HDAC family exerting multiple functions, has been found increased in melanoma and colon cancers." (PMID 41458974, 2025). "Furthermore, increased cellular proliferation and migration observed in SPOP-depleted HCT116 colon cancer cells could be partially reversed by additional depletion of HDAC6, suggesting that HDAC6 is a key downstream effector of SPOP's tumor suppressor function." (PMID 40521202, 2025). "The selective HDAC6 inhibitor ITF3756 reduced the viability of HCT116 and HT29 colon cancer cells and promoted lipogenesis." (PMID 41458974, 2025). "Deacetylation of AKAP12 at K531 by HDAC6 increases its ubiquitination, which facilitates AKAP12 proteasome-dependent degradation to promote colon cancer metastasis." (PMID 39247591, 2024). "HDAC6 is overexpressed in a variety of tumors including primary acute myeloid leukemia (AML) blasts, colon cancer, and so on, and plays important roles in various processes, such as enhanced cellular proliferation, cancer cell migration and invasion." (PMID 38554776, 2024). "It has been shown that colon cancer cells secrete GRP78 via exosomes and that this process is dependent on the activity of HDAC6, which is often overexpressed in CRC." (PMID 38258065, 2023). "Our findings demonstrate that HDAC6 promotes the phosphorylation and activation of TAK1 by deacetylating it in colon cancer cells." (PMID 36270986, 2022). "It demonstrated that K-Ras conferred SAHA resistance by upregulating HDAC6 and MYC expression in colon cancer cells." (PMID 35591851, 2022). "The results showed that knockdown of HDAC6 inhibited phosphorylation of TAK1, p38, and ADAM17 in colon cancer xenograft mouse model, which were consistent with results in vitro." (PMID 36270986, 2022). "We conclude that HDAC6, along with its corepressor partners, is an important target for SFN action in human prostate and colon cancer cells." (PMID 21624135, 2011). "Additionally, SETD7/9 was shown to suppress histone deacetylase-6 (HDAC6)-mediated activation of the ERK signaling cascade, showing that SETD7/9 has an anti-tumor role in colon cancer." (PMID 38827317, 2024). "Moreover, SET7 functions as a tumor suppressor by inhibiting the deacetylating activity of HDAC6, partially through the ERK signaling pathway in colon cancer cells." (PMID 38258065, 2023).
colon cancer (continued). "An increased expression of HDAC6 was reported in colon cancer tissue compared to the adjacent noncancerous tissue and is often associated with unfavorable disease prognosis." (PMID 38258065, 2023). "In colon cancer cell lines, a knock-down of HDAC6 resulted in reduced p-ERK expression, but not total ERK expression levels." (PMID 35159049, 2022). "To explore whether HDAC6 could affect ADAM17 expression and its activity, we measured the levels of the protein expression of ADAM17 and the cutting substrate peptides in colon cancer cells." (PMID 36270986, 2022). "In our study, we identified HDAC6 as a negative modulator of the immune microenvironment in colon cancer." (PMID 36270986, 2022). "In addition, HDAC6 knockdown did not affect the protein expression of mIL-6R in colon cancer cells." (PMID 36270986, 2022). "Compared with normal colon FHC cells, HDAC6, but not HDAC1, was highly expressed in all of the colon cancer cells examined (HCT-116, DLD1, SW480, HT-29 and SW620)." (PMID 27460191, 2016).
colorectal cancer (31 papers, 2015 to 2025). A primary or metastatic malignant neoplasm that affects the colon or rectum. "HDAC6 is associated with the development and progression of colorectal cancer (CRC) and is related to CRC poor prognosis." (PMID 41458974, 2025). "The compounds potently inhibited BRAFV600E, HDAC1, and HDAC6 enzymes and suppressed the proliferation of colorectal cancer cells harboring both wide-type BRAF and V600E mutated BRAF." (PMID 35936102, 2022). "In colorectal cancer, the expression of HDAC6 was significantly positively correlated with MYC, p65, and BCL2L1 (p < 0.01), while negatively correlated with infiltration levels of CD8+T cells." (PMID 38231305, 2024). "Colorectal cancer patients with high HDAC6 expression had worse survival comparing with that of low HDAC6 patients (p < 0.05)." (PMID 38231305, 2024). "We analyzed the correlation between HDAC6 expression and immune cell infiltration in colorectal cancer and found that HDAC6 expression was significantly negatively correlated with the infiltration level of CD8+T cells." (PMID 38231305, 2024). "We also demonstrated that MPT0G236 inhibited the activity of Class I HDACs (HDAC1, HDAC2, HDAC3, and HDAC8), as well as of a Class IIb HDAC, HDAC6, leading to the increased acetylation of α-tubulin and histone H3 in both colorectal cancer cells." (PMID 37628767, 2023). "SET7 and HDAC6 displayed reciprocal interactions, where SET7-HDAC6 interaction decreased colorectal cancer cell viability and migration." (PMID 36076996, 2022). "Snail2 interacted with HDAC6 and recruited HDAC6 to the promoter sequences of E-cadherin, which decreased E-cadherin expression in colorectal cancer cells." (PMID 36076996, 2022). "MPT0G612, an inhibitor of HDAC6, induced the apoptosis of colorectal cancer (CRC) cells and decreased the expression of programmed death ligand-1 (PD-L1)." (PMID 36076996, 2022). "While in ovarian PDX models HDAC knockdown of mainly class I members reduced PD-L1 and PD-L2 expressions, HDAC6 inhibition or knockdown of HDAC6 in colorectal cancer cells decreased IFN-γ-induced PD-L1 expression." (PMID 33562653, 2021). "Additional evidence also supported that HDAC1, HDAC2 and HDAC6 over-expression were observed in the stage III colorectal cancer tissues when compared with normal tissues." (PMID 26087180, 2015). "This further verified the adverse effect of high HDAC6 expression on colorectal cancer patient." (PMID 38231305, 2024). "Notably, a correlation between expression of Smad7 mRNA and both c-Jun and HDAC6 mRNA can also be seen in clinical material from patients with colorectal carcinoma, and high levels of HDAC6 mRNA correlate with poor survival." (PMID 32888405, 2020). "HDAC6 inhibitors may be of great significance in the study of tumor immunotherapy and related combination strategies, which provides a new strategy for tumor immunotherapy of colorectal cancer." (PMID 38231305, 2024).
colorectal cancer (continued). "This suggested that the HDAC6 inhibitor, ACY-1215, suppressed the expression of PD-L1 in colorectal cancer cells." (PMID 38231305, 2024). "Using the online database, we also found that HDAC6 was positively correlated with the downstream target genes of STAT1 or NF-κB p65, such as MYC, RELA (p65) and BCL2L1, in colorectal cancer specimens." (PMID 38231305, 2024). "In colorectal cancer cells, HCT116 and HT29, knock-down of HDAC6, blocked cell proliferation, migration and invasion in part via the MAPK/ERK signaling pathway." (PMID 36012642, 2022). "Another study found that a new HDAC6 inhibitor, MPT0G612, activated autophagy to downregulate PD-L1 levels in colorectal cancer." (PMID 36077620, 2022). "Tubacin, an inhibitor of HDAC6, promoted the extracellular release of CD133+ EVs from human FEMX-I metastatic melanoma and Caco-2 colorectal carcinoma cells, leading to the downregulation of intracellular CD133." (PMID 36076996, 2022). "In general, butyrate inhibits most HDACs, except class 2 (HDAC6 and 10) and class 3, and specifically inhibits HDAC1 and 3 in colorectal cancer cells." (PMID 29930765, 2018). "Herein, the study reveals a new mechanism by which HDAC6 down-regulates PD-L1 by regulating non-histone substrates, and provides a new strategy for the tumor immunotherapy in colorectal cancer." (PMID 38231305, 2024). "In a study, a novel HDAC6 inhibitor (MPT0G612), which induces apoptosis and inhibits IFN-γ-induced programmed death-ligand 1 in human colorectal cancer cells, was found to be a potential strategy for the combination of immune checkpoint inhibitors in the treatment of CRC." (PMID 34485153, 2021). "In our preceding study, we found that Snail2 could suppress E-cadherin expression by recruiting HDAC6 and PRC2 in colorectal cancer." (PMID 31271097, 2019). "Pulldowns using a lysate of the colorectal cancer cell line SW620 showed clear dose-dependent competition of HDAC1, HDAC2 (including co-competed members of the HDAC1/2 containing CoREST complex), and HDAC6 for both (R/S)-LA and (R/S)-LM with affinities in the range of 3–33 μM." (PMID 37322067, 2023).
hepatocellular carcinoma (30 papers, 2013 to 2026). A malignant tumor that arises from hepatocytes. "In addition, high expression of HDAC6 was associated with a poor prognosis of hepatocellular carcinoma (p = 0.046) and pancreatic cancer (p = 0.028)." (PMID 35422864, 2022). "HDAC6 was downregulated in human hepatocellular carcinoma (HCC) tissues, and it down regulation was associated with poor prognosis in liver transplantation patients." (PMID 33267897, 2020). "Hepatocellular carcinoma is prevented from progressing by HDAC6 through the formation of a transcriptional repression complex with TRIM28." (PMID 39534556, 2024). "Daphne flavone has shown significant inhibitory effects against hepatoma cells, and histone deacetylase 6 (HDAC6) has been identified as a potential target of Daphne flavonoid." (PMID 36278230, 2022). "The prognostic role of HDAC6 was further verified in the hepatocellular carcinoma (GSE14520) and pancreatic cancer (PACA-AU) datasets in GEO and ICGC, and the findings were consistent with that in the TCGA dataset." (PMID 35422864, 2022). "Sorafenib induced autophagy by increasing the expression of HDAC6 and promoting glycolysis in hepatocellular carcinoma cells." (PMID 36076996, 2022). "The authors validated HDAC6 expression in hepatocellular carcinoma tumor tissues by performing immunohistochemical analysis, which exerted a significant effect on hepatocellular carcinoma pathogenesis and progression." (PMID 34790654, 2021). "In this article, we aimed to explore the potential protective effect of curcumin against UV radiation-induced DNMT1, DNMT3A, DNMT3B, HDAC5, and HDAC6 expression in immortalized keratinocytes (HaCaT), hepatocellular carcinoma (HepG2), and lung adenocarcinoma (A549) cells." (PMID 41901340, 2026). "For example, the highly selective HDAC11 inhibitor B6 has demonstrated favorable pharmacokinetics in the treatment of metabolic dysfunction-associated fatty liver disease, and selective inhibition of HDAC6 by N-acylhydrazone can suppress hepatocellular carcinoma progression." (PMID 41444923, 2025). "In addition, HDAC6 upregulation can inhibit the mesenchymal transformation of hepatocellular carcinoma (HCC) epithelial cells by increasing the level of E-cadherin protein and reducing the levels of N-cadherin, vimentin, and MMP-9 proteins." (PMID 35449808, 2022). "The overexpression of histone deacetylase 6 was recognized as a sign of migration phenotype and tumor invasion in hepatocellular carcinoma and CCA, while its inhibition proved evident effects on the restoration and expression of the cilium in cholangiocytes and in tumor decay." (PMID 31731674, 2019). "In addition, in hepatocellular carcinoma, upregulation of hsa-miRNA-221-3p decreases the expression of HDAC6, a tumor suppressor, and promotes tumorigenesis." (PMID 31467538, 2019). "A report on the role of HDAC6 in alcohol-induced alterations in Wif-B liver cells, (a hybrid of human fibroblasts and Fao rat hepatoma cells), showed a decreased HDAC6 expression after alcohol or TSA treatment and this resulted in changes in microtubule dynamics." (PMID 23281659, 2013). "In the case of hepatocellular carcinoma (HCC), pro-inflammatory cytokines increase the amount of HDAC6 in the body." (PMID 37638049, 2023). "The loss or inhibition of HDAC6 expression resulted in increased expression of let-7i-5p, which directly inhibited the tumor suppressor thrombospondin-1 (TSP1), suggesting that the HDAC6/let-7i-5p/TSP1 pathway mediated antitumor and phagocytic activities in patients with hepatocellular carcinoma." (PMID 34638868, 2021). "The participation of HDAC10 in the HCV life cycle was previously unknown; however, an important consequence of the simultaneous inhibition of HDAC6 and HDAC10 by tubastatin A is the preservation of the antiviral activity of the drug during the conversion from RP to PS hepatoma cells." (PMID 33925399, 2021).
hepatocellular carcinoma (continued). "Upregulated HDAC6 levels have been observed in many cancer cell lines and in cohorts of oral squamous cell carcinoma (OSCC) and hepatocellular carcinoma (HCC) patients." (PMID 28668087, 2017). "However, in another study, it was found that knockdown of HDAC6 significantly upregulated the expression of HIF-1α and VEGFA in vivo and in vitro and promoted HIF-1α-mediated hepatocellular carcinoma (HCC) angiogenesis." (PMID 40260239, 2025).